SIRT1 (sirtuin 1)
Diseases named in the same sentence as SIRT1 in open-access papers (continued):
Sharing a sentence is not in itself a finding about the gene and the disease.
tumor (932 papers, 2006 to 2026). "For CRC cell metabolism, SIRT1 expression is upregulated in a glucose-deficient tumor microenvironment, leading to the deacetylation of β-catenin." (PMID 40567502, 2025). "For example, SIRT1 is associated with protective effects against tumor growth and promotes the cell death of tumor cells." (PMID 40149420, 2025). "Subsequently, SIRT1 regulates the migration of tumor-associated macrophages (TAMs) through the CXCR4/CXCL12 pathway, which inhibits the proliferation and activity of CD8+ T cells." (PMID 40567502, 2025). "The overexpression of cytoplasmic SIRT1 in Her2 types showed a significant association with tumor size (p = 0.036)." (PMID 39858444, 2025). "It is also found that the loss of miRNAs leads to unchecked SIRT1 activity, contributing to tumor growth, metastasis, and chemotherapy resistance, indicating this is one of the key processes in HCC progression." (PMID 40052151, 2025). "Compounding these issues, the context-dependent biology of SIRT1—acting as a tumor suppressor in some settings and a promoter of tumor survival in others—adds complexity and risk, particularly in oncology." (PMID 41300302, 2025). "This was in agreement with a previous report, which found that the overexpression of SIRT1 in BC tissues was associated with a low tumor grade." (PMID 39858444, 2025). "In recent years, SIRT1 has been implicated as both a tumor suppressor and a tumor promoter, depending on the cellular and molecular context." (PMID 41471349, 2025). "In 55% of HCC patients, sirtuin 1 (SIRT1) is overexpressed, which is linked to a greater tumor grade and a lower chance of survival." (PMID 40439888, 2025). "Up until now, most studies investigating the associations between advanced-staged BC (including tumor invasion and metastatic progression) and SIRT1 expression were in Southeast Asian populations." (PMID 39858444, 2025). "The miR-34a is a key regulator of tumor suppression controlling the expression of several targets involved in the cell cycle (c-MYC, E2F, CDK4 and CDK6), apoptosis (BCL2 and SIRT1) and tumor-associated invasion (c-MET)." (PMID 40755967, 2025). "Activation of the Heterogeneous Nuclear Ribonucleoprotein D (hnRNP D)/PPARG Coactivator 1 Alpha (PGC-1α) module enhances angiogenesis and invasion, whereas FOXO1-driven acetylation following SIRT1 loss suppresses tumor growth and promotes apoptosis." (PMID 41425553, 2025). "Their finding was consistent with the earlier studies, and they concluded that an elevated expression of SIRT1 exerts a tumor-suppressive role and was associated with a low frequency of LN metastasis in ER-positive BC subtypes." (PMID 39858444, 2025). "Depending on the mutational status and tumor type, SIRT1 and SIRT2 can influence both tumor promotion and suppression." (PMID 41333420, 2025). "We report that in addition to targeting SIRT1, as does its parental heliomycin, 4-dmH engages with the tumor-associated NADH oxidase (tNOX, ENOX2), as analyzed by CETSAs and molecular docking studies." (PMID 38567911, 2024). "We further addressed the cellular outcome of SIRT1 inhibition by these compounds and found that, in addition to SIRT1, the water-soluble 4-dmH preferentially targeted a tumor-associated NADH oxidase (tNOX, ENOX2)." (PMID 38567911, 2024). "We then evaluated the diagnostic and prognostic value of SIRT1 and explored its differential expression in different immune subtypes and tumor cell subtypes." (PMID 39845948, 2024).
tumor (continued). "Sirt1 influences cell viability and the apoptosis of certain solid cancer cells by regulating tumor-growth-associated signaling pathways such as the Wnt signaling and JAK2/STAT3 pathways." (PMID 38254877, 2024). "Previously, Sirt1 overexpression was associated with stage I/II/III tumor and poor prognosis in CRC patients." (PMID 39061884, 2024). "Elevated expression of SIRT1 in human NSCLCs is positively associated with advanced tumor stage, metastasis, and worse prognosis." (PMID 38443596, 2024). "The results revealed that, in addition to the previously reported interaction with β-catenin, ZMIZ2 also binds to the deacetylase SIRT1, which is closely associated with tumor progression." (PMID 39266996, 2024). "In lncRNA-Topic 4, which includes a set of 19 lncRNAs, SIRLNT (SIRT1 regulating lncRNA tumor promoter) has the top high probability of association with the topic (P(SIRLNT|lncRNA-Topic 4) = 0.6)." (PMID 38611028, 2024). "SIRT1 downregulation in the tumor cells caused them to present with punctate mitochondria and diminished functionality." (PMID 37063423, 2023). "Overexpression of SIRT1 and suppression of FoxO1 cause tumor growth and increase cell survival of cancer cells." (PMID 37987301, 2023). "Immunohistochemical (IHC) assays of the tumor tissues revealed that SIRT1 deficiency downregulated the Ki-67 proliferation marker in tumor cells." (PMID 37063423, 2023). "Clinical analysis of SIRT1 expression in tumor tissues showed the SIRT1High profile was associated with poor prognosis in CRC patients." (PMID 37063423, 2023). "We recently reported that tumor‐associated neutrophils promoted the lung metastasis of BC via the SIRT1‐neutrophil‐NET axis, and the Th1/Th2 differentiation imbalance and impaired antigen‐presenting cell function were also related to BC development." (PMID 38053815, 2023). "On the other hand, PI3K activation causes SIRT1 to move into the nucleus, where it can act as a tumor promoter." (PMID 37175631, 2023). "SIRT1 is known to be associated with metastasis, with a role in cell proliferation and tumor development." (PMID 36142156, 2022). "As shown in the Kaplan–Meier curve, co-expression of Sirt1 and nuclear RXRα was associated with significant longer survival time after diagnosis in advanced tumour stages (FIGO III/IV)." (PMID 34870752, 2022). "By transfecting wild‐type or dead‐enzyme mutants of SIRT1 or SIRT2 into tumour cells, we found that the loss of SIRT2 deacetylase activity resulted in consistent levels of LIFR‐K620 acetylation." (PMID 35172032, 2022). "Co-expression of nuclear RXRα and cytoplasmic (p = 0.026) or nuclear (p = 0.041) Sirt1 was associated with significantly increased overall survival in advanced tumour stages." (PMID 34870752, 2022). "In this study, it was observed that increased tumor growth and poor prognosis were associated with the high expression of SIRT1, a protein that supports cell survival and angiogenesis in ESCC patients." (PMID 36142861, 2022). "Silent mating type information regulation 1 (SIRT1) an autophagy-related protein is associated with poor prognosis, tumor invasiveness, and metastasis in CRC patients." (PMID 35912261, 2022). "SIRT1 overexpression plays a promotive role in tumorigenesis and is closely associated with tumor invasion and lymph node metastasis in NSCLC." (PMID 34381712, 2021). "Previous studies have confirmed that PGC1-α is associated with Sirt1 in a variety of neoplastic diseases, and that PGC1-α is highly correlated with mitochondria." (PMID 32570218, 2020).
tumor (continued). "Further, the tumor-promoting phosphoinositide 3-kinase/insulin-growth factor 1 receptor (PI3K/IGF-1R) signaling cascade is implicated in regulating SIRT1 stability in the cytoplasm." (PMID 33178616, 2020). "SIRT1 regulates a large number of proteins often functionally implicated in tumor development and progression." (PMID 33042011, 2020). "Sirtuin 1 (Sirt1) is one of the key members of the sirtuin family and its induction is associated with diminished viability and proliferation of tumor cells." (PMID 32163546, 2020). "The study stated that an overexpression of SIRT1 is found in HCC cell lines compared to the controls, and there was a statistical association between advancement of the tumor grade and expression of SIRT1." (PMID 32607257, 2020). "In support of this, the association of CRC progression with TIM-3 and SIRT1 expression in tumor tissues have been reported." (PMID 32393998, 2020). "We also found SIRT1 was significantly associated with gender, tumor stage and T (primary tumor) and its expression levels increased with time." (PMID 32998713, 2020). "Several studies have analysed SIRT1 gene polymorphisms and expression in association with various types of tumours." (PMID 31747893, 2019). "In the current study, we compared the differences in migration and invasion between tumor cells overexpressing wild-type SIRT1 or NLS-mutated SIRT1 and further explored the related mechanisms in vitro." (PMID 31317367, 2019). "In agreement, SIRT1 upregulation has been shown to be associated with tumour progression and metastasis in NPC biopsies." (PMID 31727006, 2019). "Specifically, in NSCLC, SIRT1 is highly expressed in tumor issues and is tightly associated with the poor overall survival of patients with NSCLC." (PMID 31133857, 2019). "FOXO1 represses GC growth and angiogenesis; inactivation of FOXO1 is associated with SIRT1 expression in human GC tissues and xenograft GC tumor tissues." (PMID 31689236, 2019). "The authors then suggested an oncogenic role of SIRT1 in association with EMT in tumor invasion of TNBC subtype." (PMID 30380732, 2018). "Conversely, other studies showed that overexpression of SIRT1 caused the suppression of DNA damage repair proteins and factors involved in tumor suppression, and thus led to increased tumor growth and cell survival." (PMID 29636061, 2018). "After long-term feeding, resveratrol inhibited age-associated liver spontaneous neoplasms and increased expression of SIRT1 and DLC1 and their interaction." (PMID 28903430, 2017). "Our findings implicate miR-449a as a tumor suppressor in ERG-associated CaP cells by suppression of SIRT1." (PMID 26988912, 2016). "High Beclin-1/high SIRT1 expression was also associated with tumor size (p = 0.002), histological grade (p = 0.001), LN metastasis (p < 0.001), tumor invasion (p = 0.026), TNM stage (p < 0.001), and VCE (p = 0.030)." (PMID 28070138, 2016). "Tumor infiltrating CD4+T cells isolated from the SIRT1-deficient groups had a higher IL-9+ ratio than the WT group." (PMID 27589682, 2016). "High SIRT1 expression was associated with patient age (p = 0.046), tumor size (p = 0.016), histological grade (p = 0.007), LN metastasis (p < 0.001), tumor invasion (p = 0.015), and TNM stage (p < 0.001)." (PMID 28070138, 2016). "We further investigated the mechanism underlying the regulatory effects of MSCs-Sirt1 on tumor growth." (PMID 27782173, 2016). "Consistently, miR-200a levels in tumor samples or blood were inversely associated with SIRT1 expression in patients with in situ or invasive breast carcinoma." (PMID 27379175, 2016). "The complex mechanisms underlying Sirt1 signaling during carcinogenesis remain controversial, as it can serve both as a tumor promoter and suppressor." (PMID 26959057, 2016).
tumor (continued). "The aim of this study was to establish a protein expression profile of SIRT1-7 in PDAC tumours and to determine if there were any associations between SIRT1-7 expression, clinico-pathological parameters and patient outcome." (PMID 26121130, 2015). "In this line, a recent study has demonstrated an increased SIRT1 expression in different colonic lesions, including polyps, adenomas and neoplasia, which was associated with the grade of malignancy and invasiveness." (PMID 26437418, 2015). "Conversely, other studies showed that overexpression of SIRT1 caused the suppression of DNA damage repair proteins and factors involved in tumor suppression, and led to increased tumor growth and cell survival." (PMID 25486244, 2014). "High SIRT1 expression was significantly associated with several poor prognostic factors such as advanced tumor progression (P < 0.001), positive lymphatic invasion (P = 0.01), positive venous invasion (P < 0.001), and advanced stage (P = 0.03)." (PMID 25146318, 2014). "SIRT1 positive expression was significantly associated with tumor progression, lymphangiogenesis, LVI and poor survival in pN0 ESCC patients." (PMID 25922660, 2014). "Significant associations were observed between SIRT1 expression and size of the tumor, tumor number, and TNM stage (P = 0.043, P = 0.031, P = 0.038, respectively) for the 99 patients with HCC." (PMID 25522783, 2014). "We presume that SIRT1 protein expression in HCC was significantly associated with the pathological features of tumor size, tumor number, and TNM stage." (PMID 25522783, 2014). "In the present study, we found that the SIRT1 expression is associated with higher tumor stage and poorer differentiation status, and poor prognosis, indicating that at least in advanced NSCLC, SIRT1 expression was parallel with the disease severity." (PMID 24223900, 2013). "Univariate analysis showed four statistically significant variables associated with the prognosis of NSCLC: tumor stage (P<0.001), smoker (P=0.024), tumor differentiation (P=0.003) and SIRT1 expression (P<0.001)." (PMID 24223900, 2013). "Our results suggest that the tumor attenuation previously observed in APC+/min mice carrying a systemic deletion of SIRT1 was a tissue-specific effect of SIRT1-deficiency." (PMID 23799088, 2013). "Cellular analyses have implicated SIRT1 in tumour cell growth, and poor prognosis in hepatocellular carcinoma." (PMID 24258275, 2013). "We found that the SIRT1 expressions were significantly associated with the tumor stage, tumor size and differentiation status." (PMID 24223900, 2013). "We found that SIRT1 expression were significantly associated with the tumor stage, size and differentiation status." (PMID 24223900, 2013). "For instance, activation of SIRT1 by resveratrol was shown to limit cell growth and reduce tumour formation in BRCA1-deficient tumour cells as well asTrp53+/−;Sirt1+/− mice." (PMID 24223900, 2013). "Upon assessment of the microvessel density index by CD31 antibody staining, the tumor growth enhancement observed in the SIRT1 knock-in transgenic mice was associated with an increase in tumor vascularization." (PMID 23028940, 2012). "The data demonstrated that the reduction in tumor development is caused by the ability of Sirt1 to deacetylate β-catenin and promote cytoplasmic localization of the nuclear-localized oncogenic form of β-catenin." (PMID 21549004, 2011).
tumor (continued). "SIRT1 has been shown to be involved in the maintenance of silencing associated with abnormal promoter region CpG island DNA methylation in tumor suppressor genes." (PMID 18704159, 2008). "This overexpression is associated with increased tumor aggressiveness, suggesting that SIRT1 may contribute to the malignant phenotype in HER2+ tumors." (PMID 41300302, 2025). "Additionally, SIRT1 is implicated in reducing oxidative stress and inflammation, and acts as a tumour suppressor." (PMID 39985566, 2025). "Moreover, the cytoplasmic expression of SIRT1 in HER2-positive BC was associated with a larger tumor size (p = 0.036) and lymph node metastasis (p = 0.045)." (PMID 39858444, 2025). "In TNBC, however, SIRT1 is downregulated, and the loss of SIRT1 may promote tumor invasion and survival by impairing lysosomal integrity." (PMID 40165290, 2025). "Also, the link between SIRT1 protein loss and tumor emergence has been evidenced by several models, where SIRTs knockout mice are more prone to tumor formation." (PMID 39858444, 2025). "SIRT1, as the most tumor-associated subtype of the sirtuins family, is a regulator of autophagy." (PMID 40229278, 2025). "Notably, SIRT1 and other sirtuin family members have been implicated in tumor suppression, supporting a context-dependent role of sirtuins that is not yet fully understood." (PMID 40517236, 2025). "High levels of SIRT1 have been associated with inhibited tumor proliferation in mouse model." (PMID 40567502, 2025). "High SIRT1 levels are associated with reduced overall survival and increased tumor grade and stage." (PMID 41300302, 2025). "Interestingly, this situation was also linked to a marked reduction in SIRT1 expression within the tumor tissue itself." (PMID 41425553, 2025). "In particular, in different tumor microenvironments, SIRT1 mutations may exert their effects through distinct signaling pathways or molecular mechanisms." (PMID 39845948, 2024). "In UCEC, SIRT1 mutations may promote tumor cell proliferation and invasion by affecting estrogen signaling pathways." (PMID 39845948, 2024). "Higher SIRT1 levels had been associated with resistance to the kinase inhibitor sorafenib and to multiple other antitumor agents including cisplatin, oxaliplatin, 5-fluorouracil, doxorubicin, and pirarubicin in a variety of tumours." (PMID 38369747, 2024). "Moreover, NAMPT, which is downstream of G-CSF (CSF3) receptor signaling, promotes the tumorigenic conversion of tumor-associated neutrophils (TANs), enhancing angiogenesis via SIRT1 activity." (PMID 38116009, 2023). "It has been shown that SIRT1 gene expression was high in the 67NR group, which may be associated with the tumor-suppressor effect of SIRT1." (PMID 36142156, 2022). "Mechanistically, we showed that transcriptional factor Bcl6 co-opted the demethylase Tet2 and the deacetylase SIRT1 to confer the epigenetic imprinting and mitochondrial metabolic traits to SMMs, bolstering the stability and longevity of trained immunity in tumor-associated macrophages (TAMs)." (PMID 36542153, 2022). "Furthermore, increased expression of SIRT1 and mtOXPHOS proteins in tumor tissues of lung adenocarcinoma patients is associated with recurrence and poor prognosis." (PMID 36263432, 2022). "A recent study demonstrated that high SIRT1 expression in patients was associated with better overall survival, suggesting that SIRT1 may act as a tumor suppressor." (PMID 36230643, 2022). "It has been reported that SIRT1 deficiency in MDSCs induces their phenotypic change to M1 macrophages via the mTOR-HIF1α glycolytic pathway, decreasing their suppressive function, promoting inflammation and delaying tumor growth in mice." (PMID 34828304, 2021). "Furthermore, SIRT1 is an important marker of poor prognosis; SIRT1 is associated with poor clinicopathological manifestations, including tumor size, lymph node metastasis, and advanced tumor invasion." (PMID 34934771, 2021).